NRP1 (neuropilin 1)
Diseases named in the same sentence as NRP1 in open-access papers (continued):
Sharing a sentence is not in itself a finding about the gene and the disease.
tumor (continued). "As various types of NRP1 blockade can modulate multiple signaling pathways of proangiogenic growth factors, this approach has also been expected to increase antitumor efficacy of some antiangiogenic agents by making tumor vessels vulnerable to anti-VEGF therapy." (PMID 32560565, 2020). "The heptapeptide (ATWLPPR) targeting the NRP-1 protein was also used in the study by Hu, in which this peptide was associated with CGKRK forming the dual-decorated nanoparticulate (designated AC-NP) to achieve a dual-targeting effect for angiogenic blood vessels and the tumor microenvironment." (PMID 32599834, 2020). "We obtained results on the correlation between TPPP3 expression and marker genes of tumor infiltration-associated immune cells, including CD8+T cells (CD8A and CD8B), B cell (CD19 and CD79a), and Myeloid dendritic cell (HLA-DPB1, HLA-DQB1, HLA-DRA, HLA-DPA1, CD1C, NRP1, and ITGAX)." (PMID 33083464, 2020). "Our data indicate that IDB0076 may also trigger cointernalization of a cognate receptor (VEGFR1 for VEGFB and PlGF2) by inducing cellular internalization of NRP1 and should break the resistance to bevacizumab by blocking these growth factors taking part in tumor angiogenesis." (PMID 32560565, 2020). "Thus, NRP1 expressed on CAF might also stimulate EMT which increases tumor cell migration and invasion worse prognosis." (PMID 32766254, 2020). "As NRP-1 is expressed by the endothelial cells in all tissues, peptides containing cryptic CendR owe their target selectivity to a combination of binding to primary receptor with a tumor-specific expression pattern, and to a proteolytic activation to expose the CendR sequence in the target organ." (PMID 32497513, 2020). "In addition, it has been demonstrated that tumor levels of NRP1 might aid the selection of patients with advanced or metastatic GC who might benefit from the combination treatment of bevacizumab and chemotherapy." (PMID 32508529, 2020). "However, since NRP1 is expressed in addition to tumor tissue in various tissues, a NRP1-directed antibody is rapidly eliminated, interfering with physiological tissue functions and also reducing its uptake by tumor cells." (PMID 30717262, 2019). "This transfer and activation of NRP1 via sEVs from oncogenic cells to recipient endothelial cells may alter endothelial cell surface interactions and increase their responsiveness to soluble angiogenic ligands in the tumor microenvironment." (PMID 31852509, 2019). "Therefore, in the tumor inflammatory microenvironment, ionizing radiation effects on NRP1 may regulate IL-17, TNF, IL-6, IL-8 and other inflammatory factors to enhance the radiation resistance of A549 cells." (PMID 31417646, 2019). "Moreover, CD8+ TIL from mice treated anti-Nrp-1 i.p. plus anti-PD-1 combination or anti-Nrp-1 i.t. plus anti-PD-1 combination kill more efficiently MC-38 tumour cells ex vivo than TIL from mice treated with anti-Nrp-1 i.t. or i.p. alone, anti-PD-1 alone or isotype control mAb." (PMID 31350404, 2019). "Furthermore, we measured Nrp1 and Nrp2 in serum samples from 45 tumor patients." (PMID 30758083, 2019). "In addition, the published data indicate that a tumor was suppressed by silencing NRP-1." (PMID 30978940, 2019). "In addition, secondary acquired tumor resistance to therapies (including the most innovative and targeted ones) arises from salvage molecular pathways supporting cancer cell viability, such as those upregulated by NRP1." (PMID 31027288, 2019). "Although the composition and function of these tumor-infiltrating Treg cells is still a topic of debate, evidence suggest that both thymically-derived natural Treg cells, characterized by high expression of neuropilin-1, and induced Treg cells play important role in regulating anti-tumor immunity." (PMID 31058083, 2019).
tumor (continued). "In the AVAGAST trial, it has been shown that the assessment of circulating VEGF-A and tumor levels of NRP1 could aid the selection of patients with advanced or metastatic gastric cancer who are more likely to benefit from the addition of bevacizumab to the chemotherapeutic protocol." (PMID 31027288, 2019). "Moreover, Nrp1 deficiency on Foxp3+ Treg cells has been associated with lack of immune suppression, predominantly affecting tumor growth and worsening EAE severity." (PMID 31068948, 2019). "Moreover, expression of Nrp-1 on PD-1high CD8+ TIL may also permit easier quantification of this T-cell pool displaying tumour reactivity." (PMID 31350404, 2019). "Thus, NRP1 ablation alone may constitute a ‘two-hit’ mechanism by which these cells slow tumor progression through reversing the M2-like phenotype while simultaneously stunting the neoangiogenic potential of GAMs." (PMID 30479695, 2018). "Therefore, dual-ανβ3-integrin-NRP1-targeting paramagnetic liposome with a RGD-ATWLPPR heterodimeric peptide might be a potent system for molecular imaging of tumor." (PMID 30483904, 2018). "Furthermore, the function of NRP‐1/NRP‐2 heterodimers should be investigated in PDAC as their similar but unique properties may confer different advantages to the tumor." (PMID 30216699, 2018). "Moreover, Nrp-1 is an important factor for tumor progression, which is overexpressed in PDAC." (PMID 29373514, 2018). "Additionally, NRP1 was detected in the surrounding tumor tissue." (PMID 30027561, 2018). "Thus, we hypothesized that by targeting two molecules simultaneously in tumor angiogenesis, e.g., ανβ3-integrin and neuropilin-1, could enhance the signal of paramagnetic liposome-based MR imaging of tumor." (PMID 30483904, 2018). "The Nrp1 substitute, Klrd1 (Killer Cell Lectin-Like Receptor Subfamily D, Member 1), an antigen expressed on Natural Killer cells, may also be considered as target to block tumor dissemination." (PMID 28632792, 2017). "In addition, knockdown of Nrp1 inhibits MMTV-Wnt1 tumor growth in xenograft." (PMID 28887477, 2017). "The miR-148b suppresses proliferation and invasion of HCC cells by direct targeting neuropilin-1, the molecules could be detected not only in in body fluids (serum, plasma, cerebral spinal fluid and urine) but also tumor tissues, it expression was decreased in HCC." (PMID 29100442, 2017). "However, in KRASwt cells, NRP1 knockdown suppressed cell viability and tumor growth." (PMID 29018205, 2017). "NRP1 expression on pDCs could be involved in tumor trafficking of pDCs or tolerance induction." (PMID 29067024, 2017). "It should be noted that other Nrp1-mediated pathways, particularly VEGFA, semaphorin 3A, and HGF signaling may also play important roles in the overall modalities of how GAMs associate with the tumor microenvironment." (PMID 26755653, 2016). "Thus, inhibition of either Nrp-1 or IL-10 can affect tumor-derived TGF-β1 levels." (PMID 27075020, 2016). "Together, these NRP-1 findings in conjunction with studies highlighting the role of TGFβ signaling in EndMT, helped us postulate that NRP-1 could be playing a previously unrecognized regulatory role in TGFβ1-induced EndMT and potentially contributes towards tumor fibrosis." (PMID 27542226, 2016). "Reductions in class 3 semaphorins were observed, which could enhance VEGF signaling by making more NRP1 available; lower Sema3 levels could also enhance angiogenesis by removing inhibitory signals mediated by plexins (i.e. the brakes on tumor angiogenesis are removed)." (PMID 26341082, 2015). "Furthermore, NRP1 expression correlates with more aggressive tumor behavior." (PMID 25954957, 2015). "Moreover, inhibition of NRP-1 may synergize with immune checkpoint inhibitors, delaying tumor progression and development of resistance." (PMID 26090340, 2015). "Besides, the role of NRP1 in promoting tumor angiogenesis is very well established." (PMID 26097868, 2015).
tumor (continued). "However, in certain circumstances, vascular NRP1 signaling can be detrimental, as it may promote cancer by enhancing tumor angiogenesis or contribute to tissue edema by increasing vascular permeability." (PMID 24521511, 2014). "Interestingly, C-end rule peptides with a C-terminal arginine residue in a configuration similar to that of VEGF-A bind NRP1 to induce vascular permeability, and this property may be exploited to enhance tumor penetration of chemotherapeutic drugs." (PMID 24521511, 2014). "Thus, Nrp1 may represent a direct tumor target and also a target for immunotherapy by modulation of Treg activity." (PMID 25343644, 2014). "Furthermore, patients with high peritumoral NRP-1 expression had a markedly lower MVD in the tumor tissue (3.22%±0.23% vs. low peritumoral NRP-1: 7.78%±0.40%; p = 0.012) and in the peritumoral tissue (0.43%±0.02% vs. low peritumoral NRP-1: 2.78%±0.06%; p = 0.024)." (PMID 25333267, 2014). "How VEGF and its co-receptor Nrp1 influence the plane of cell division is unclear; and establishing this may very well require single-cell studies of the perivascular niche Cancer Stem Cells exposed to tumor-cell derived VEGF." (PMID 25120491, 2014). "Thus, we can infer that the reduction in tumor growth may have been due to the decrease in NRP1, which was curbed by miR-338." (PMID 24736504, 2014). "Thus, we inferred that miR-338 inhibited tumor growth by curbing NRP1 expression in vivo." (PMID 24736504, 2014). "Moreover, we have observed the involvement of NRP1 in tumor-endothelial interaction." (PMID 22448259, 2012). "However, treatment of clone 2 with anti-Sema 3A or anti-NRP1 blocking antibody drastically induced cell migration as compared to clone 2-derived cells alone demonstrating that tumor derived Sema 3A inhibits tumor cell motility through NRP1 dependent autocrine manner." (PMID 22448259, 2012). "An exogenous expression of NRP-1 has been shown to induce a higher degree of angiogenesis in human dermal micro vascular endothelial cells and human umbilical vein endothelial cells, as well as in prostrate cell lines leading to the formation of larger tumours." (PMID 23185562, 2012). "Similarly, knockdown of Nrp1 in renal cell carcinoma cells resulted in poor tumor growth." (PMID 22948112, 2012). "NRP-1 was shown to orchestrate communications between myofibroblasts and soluble fibronectin that promote α5β1 integrin–dependent fibronectin fibril assembly, matrix stiffness, and tumor growth, underscoring its role in the activation of tumour microenvironment." (PMID 23185562, 2012). "However, the fact that the shRNA-mediated silencing of NRP-1 resulted in a complete abrogation of the in vitro as well as in vivo tumorigenesis and angiogenesis clearly underscores that NRP-1 plays a deterministic role in the vasculogenic mimicry and tumour growth of HT1080 cells." (PMID 23185562, 2012). "A major implication of this study is that therapeutic strategies targeting NRP1 in tumour cells may be particularly useful in combination with other drugs for combating tumour survival, growth, and metastatic spread independently of an antiangiogenic effect of blocking NRP1." (PMID 20087344, 2010). "If the VEGF165-NRP1-c-MET pathway is required for Mcl-1 expression and survival in PCa cells, it would be intriguing to evaluate whether targeting NRP1 could interrupt both NRP1-c-MET signaling in tumor cells (survival) and NRP1-VEGF-Rs signaling in endothelial cells (angiogenesis)." (PMID 20085644, 2010). "Since migration of tumour cells plays a key role in neoplastic spread, invasion of surrounding tissue, and formation of metastasis, these findings indicate a key role for NRP1 in the motility of carcinoma cells, which may contribute to tumour progression and metastatic potential." (PMID 20087344, 2010).
tumor (continued). "Since anoikis resistance may correlate with the ability of cells to survive detachment from the primary tumour mass and proliferate after migration to a distant site, targeting NRP-1 may increase anoikis in tumour cells and thereby decrease formation of metastases." (PMID 15956974, 2005). "Furthermore, the possibility of targeting therapies to decrease the level or function of NRP-1 in NRP-1-overexpressing tumours may lead to enhanced chemosensitivity in a previously chemoresistant tumour." (PMID 15956974, 2005). "Furthermore, expression of NRP-1 in tumour cells enhances binding of VEGF-165 to these cells." (PMID 12618892, 2003). "NRP-1, which specifically binds VEGF165 and enhances its interaction with VEGFR2, has been identified in vascular endothelial and tumor cells." (PMID 40507480, 2025). "Another interesting observation here is the presence of signaling by the VEGF pathway, which involved two upregulated genes (KDR, VEGFA) and three downregulated genes (NRP1, PRKACB, ROCK1) in G2 tumor AOIs compared to G1." (PMID 39245631, 2025). "The NRP-1 gene specifically binds VEGF165 and increases VEGF165 binding to VEGFR2 in vascular endothelial and tumor cells." (PMID 40507480, 2025). "We also observed abnormal elevation of TIM3, CD39, NRP1, and PD1 expression on infiltrating CD8+ T cells in tumor tissues." (PMID 40040705, 2025). "The low-risk group exhibited significantly elevated expression levels of HHLA2, NRP1, and TNFSF15, suggesting a less immunosuppressive tumor microenvironment." (PMID 40243888, 2025). "Sema3A binds to Plexin A requires NRP1, found on CD4+ regulatory T-cells and tumor-infiltrating CD8+ T cells." (PMID 40277760, 2025). "In this review, we have emphasized NRP1 and its role in signaling between VEGFA and semaphorins, its role in immune cells, and the tumor microenvironment." (PMID 40277760, 2025). "Chang Liu reported that CD8+ T cell-restricted NRP1 deletion exhibited substantially enhanced protection from tumor rechallenge and sensitivity to anti-PD1 immunotherapy, making NRP1 a unique immune memory checkpoint." (PMID 40277760, 2025). "At the molecular level, NRP-1 functions as a co-receptor for vascular endothelial growth factor (VEGF), a key mediator of tumor angiogenesis." (PMID 40430075, 2025). "Pro-tumor elements, such as regulatory T cells (Tregs) and MDSCs, create an immunosuppressive environment, inhibiting anti-tumor immunity via cytokines (TGF-β and IL-10) and immune checkpoint molecules (PD-L1, CTLA-4, TIM-3, TIGIT, and NRP1)." (PMID 40908470, 2025). "An anti-NRP1 mAb, MNRP1685A, is currently in Phase I clinical trials for patients with progressive solid tumors and has been shown to reduce tumor burden significantly via blockade of the VEGF pathway." (PMID 40277760, 2025). "These exosomes are originated from the ALIX-derived MVBs in the endocytic pathway, which occupied with NRP1 to promote CD8 + T cell exhaustion, subsequently facilitates tumor progression." (PMID 40908470, 2025). "Given that NRP1 is involved in tumor progression across various cancer types, our study identified synchronous changes and positive correlation between EZH2 and NRP1 in CRC." (PMID 40314246, 2025). "NRP-1, which specifically binds to VEGF165 and increases the binding of VEGF165 to VEGFR2, has been identified in vascular endothelial and tumor cells." (PMID 40507480, 2025). "In this study, we examined how certain proteins—neuropilin-1 and glial fibrillary acidic protein (GFAP)—are distributed in tumor tissue and how they relate to blood vessels, immune cells, and tumor behavior." (PMID 40805120, 2025). "NRP1 is a co-receptor for VEGF and semaphorin signaling that is involved in critical tumor processes such as angiogenesis, metastasis, and tumor progression." (PMID 40805120, 2025). "In contrast, minimal fluorescence was detected in NRP1- and GLUT1-negative NCI-H1299 cells, underscoring NGF's selective targeting of NRP1-positive tumor cells." (PMID 40048021, 2025).
tumor (continued). "These patterns were validated across multiple datasets, with significantly elevated transcript levels of NRP1 and NRP2 in tumour samples compared to healthy tissues (p<0.001)." (PMID 40134439, 2025). "Anti-NRP1 mAbs specific to the b1/b2 domain have been developed, which interact with VEGF165; these mAbs can inhibit VEGF165 isoform-induced tumor growth-promoting angiogenesis." (PMID 40277760, 2025). "Preliminary studies reveal that NRP-1 and NRP-2 inhibitors can efficiently limit angiogenesis and reduce the tumor’s potential to metastasize, making them promising therapeutic targets." (PMID 40430075, 2025). "Nevertheless, NCAM1, NRCAM, SLIT2, ALCAM, NRP1, and NRP2 also showed mild expression in Stage 4 tumor cells (primarily in cluster cIV)." (PMID 40448172, 2025). "Tumor cell-secreted PDGF-B converts MSCs into pericytes and recruits them via interaction with neuropilin-1, thus promoting angiogenesis." (PMID 40676710, 2025). "Chang Liu and his team studied the role of NRP1 in CD8+ T cells and suggested that it is an immune checkpoint of T cell memory and targeting NRP1 can facilitate the restoration of durable anti-tumor immunity." (PMID 40277760, 2025). "Molecular modeling has demonstrated that genetic fusion of DR5-B with the SRH and iRGD peptides not only enables the engagement of additional tumor targets VEGFR2 and integrin αvβ3/NRP-1, but also improves the interaction with DR5 receptor." (PMID 40841907, 2025). "It has been shown that NRP1 is a key co-receptor for VEGF-mediated NSCLC cell survival and tumour growth." (PMID 40820676, 2025). "NRP1 binds to various extracellular ligands, including vascular endothelial growth factor (VEGF) and transforming growth factor β1, leading to tumour angiogenesis and cell migration." (PMID 40820676, 2025). "ShRNA-mediated NRP1 knockdown in KRAS wildtype cells increased cell viability and tumor growth by decreasing the SMAD2 phosphorylation, whereas a KRAS mutant reverses the increased viability and leads to tumor inhibition." (PMID 40277760, 2025). "Once bound to the integrins, iRGD also binds to neuropilin-1 (NRP-1) and triggers a process known as the tumor-penetrating peptide (TPP) effect, which facilitates deep penetration of the liposomes into the tumor tissue." (PMID 39199757, 2024). "Neuropilin-1 (NRP-1) is a cell surface receptor that plays a crucial role in cell signaling, angiogenesis, and tumor progression." (PMID 39598465, 2024). "We found that YAP knockdown in vivo led to slower tumor growth after irradiation and the expression of YAP and NRP1 dramatically increased." (PMID 39187525, 2024). "The Nrp1 antagonist, Fc(AAG)-TPP11, selectively inhibits the function and stability of Nrp1+ Tregs in tumors, thereby facilitating tumor clearance." (PMID 38509593, 2024). "Deletion of NRP1 in both CD4+ and CD8+ T cells enhance CD8+ T-cell infiltration into tumours and restricted tumour growth in animal models." (PMID 38609390, 2024). "Here we demonstrate that Neuropilin-1 (NRP1) and Plexin-A1 and Plexin-A4 are upregulated on stimulated CD8+ T cells, allowing tumour-derived SEMA3A to inhibit T cell migration and assembly of the immunological synapse." (PMID 38609390, 2024). "The contribution of NRP1 to ERK activation was monitored in CAD cells, a neuron-like cell line modified from the Cath.a catecholaminergic cell line obtained from a mouse tumor." (PMID 39589827, 2024). "We first quantified NRP1 expression on CD8+ T cells from peripheral blood (PBMCs) and CD8+ TILs within tumor and tumor-adjacent tissue." (PMID 38609390, 2024). "Butyrate diminishes the interaction between NRP-1 and VEGF, thereby inhibiting tumor angiogenesis and tumor cell survival." (PMID 39710789, 2024). "NE was shown to target tumor cells via neuropilin-1 (NRP1), which is highly expressed on surface of many tumor cells." (PMID 39068444, 2024).